BHMT (betaine--homocysteine S-methyltransferase)
Diseases named in the same sentence as BHMT in open-access papers (continued):
Sharing a sentence is not in itself a finding about the gene and the disease.
cancer (5 papers, 2015 to 2020). A tumor composed of atypical neoplastic, often pleomorphic cells that invade other tissues. "In the betaine part, the expression of SLC44A4, CHDH, and BHMT was disordered across cancers and had a general downward trend." (PMID 31828117, 2019). "Western blotting of carbonic anhydrase I (CA I), fumarate hydratase (FH), and betaine–homocysteine S-methyltransferase 1 (BHMT) were performed and definitely showed they were down-regulated in the cancer tissues of HCC with PVT, compared to HCC without PVT." (PMID 28785178, 2017). "Genotyping for BHMT 716A>G, DHFR 19bp ins/del, MTHFD1 1958G>A, MTHFR 677C>T, MTR 2756A>G, MTRR 66A>G, RFC1 80G>A, SHMT1 1420C>T, TCII 776C>G and TS 2rpt-3rpt was performed in 102 cancer patients and 363 cancer-free subjects." (PMID 28968444, 2017). "Betaine–homocysteine S-methyltransferase 1 (BHMT), isovaleryl-CoA dehydrogenase (IVD), short-chain specific acyl-CoA dehydrogenase (CRAT) and arginase-1 were all down-regulated in cancer tissues of HCC without PVT and further deceased in the cancer tissues of HCC with PVT." (PMID 28785178, 2017).
cardiovascular disease (4 papers, 2014 to 2022). "BHMT and MS enzymes are crucial since increased Hcy levels are associated with cardiovascular disease, and with other diseases that may be consequential to cardiovascular disease or to disruptions in metabolism." (PMID 26213999, 2015). "More researches are needed to understand the role BHMT rs10037045 plays in atherogenesis and cardiovascular diseases, and its interaction with CBS rs2851391." (PMID 27822905, 2017).
liver (2 papers, 2018 to 2025). "The severity of alcoholic liver injury was shown to be attenuated by SAM, betaine, and phosphatidylcholine supplementation or in transgenic extrahepatic expressions of BHMT." (PMID 29534433, 2018).
kidney diseases (1 paper, 2024). "The decreased level of ALB has been proven to be associated with the severity of kidney diseases.Another protective gene BHMT is a novel prognostic biomarker for various diseases." (PMID 38961491, 2024).
neurodegenerative disease (1 paper, 2013). A disorder of the central nervous system characterized by gradual and progressive loss of neural tissue and neurologic function. "BHMT may have a neuroprotective role in the brains of hibernating mammals and further research on this system could expand our biomedical understanding of certain cerebrovascular and neurodegenerative disease processes." (PMID 24376891, 2013).
BHMT also shares sentences with these, for which no sentence is quoted: breast carcinoma (2 papers); neural tube defect (2); alcoholism (1); Alzheimer disease (1); anencephaly (1); cholestasis (1); chronic renal failure (1); cleft palate (1); colorectal adenoma (1); COVID-19 (1); endothelial dysfunction (1); haemochromatosis (1); Hyperinsulinemia (1); hyperlipidemia (1); hyperuricemia (1); infection (1); Insulin resistance (1); ischemia (1); liver fibrosis (1); metabolic disorders (1); myelomeningocele (1); nasopharyngeal carcinoma (1); orofacial cleft (1); polycystic ovaries (1); renal carcinoma (1); renal cell carcinoma (1); renal failure (1); renal oncocytomas (1); schizophrenia (1); type 1 diabetes (1).